FSAF1 (40S small subunit processome assembly factor 1)
Description:
Part of the small subunit (SSU) processome, first precursor of the small eukaryotic ribosomal subunit. During the assembly of the SSU processome in the nucleolus, many ribosome biogenesis factors, an RNA chaperone and ribosomal proteins associate with the nascent pre-rRNA and work in concert to generate RNA folding, modifications, rearrangements and cleavage as well as targeted degradation of pre-ribosomal RNA by the RNA exosome. Prevents helicase DHX37 to be recruited before post-A1 state.
Synonyms: C1orf131; DKFZp547B1713
Tractability: Small molecule: a structure with a bound ligand is known.
Gene: Protein-coding gene on chromosome 1 (231,223,763 to 231,241,187, reverse strand). Ensembl gene ENSG00000143633.
Subcellular location: Chromosome; Nucleus, nucleolus
Gene Ontology:
Molecular function: RNA binding
Biological process: ribosomal small subunit biogenesis; maturation of SSU-rRNA
Cellular component: chromosome; small-subunit processome; nucleolus
Genetic constraint (gnomAD): Loss-of-function variants: 23 observed, 29.65 expected, observed/expected ratio (o/e) 0.78, 90% interval 0.56 to 1.1. The upper end of that interval is the gene's LOEUF score, 1.1, which puts it in group 4 of 6, group 1 being the genes least tolerant of losing a copy. Missense variants: 296 observed, 342.43 expected, observed/expected ratio (o/e) 0.86, 90% interval 0.79 to 0.95. Synonymous variants: 122 observed, 124.11 expected, observed/expected ratio (o/e) 0.98, 90% interval 0.85 to 1.14.
Homologues: Orthologues: chimpanzee C1H1orf131 (98% identical), macaque C1H1orf131 (93% identical), dog FSAF1 (74% identical), pig FSAF1 (68% identical), rat C19h1orf131 (65% identical), mouse Fsaf1 (65% identical), guinea pig FSAF1 (60% identical), tropical clawed frog fsaf1 (37% identical), zebrafish fsaf1 (30% identical), Drosophila melanogaster CG1738 (18% identical).
Diseases named in the same sentence as FSAF1 in open-access papers:
FSAF1 is named in the same sentence as 10 diseases in open-access papers, as found by Europe PMC text mining. Sharing a sentence is not in itself a finding about the gene and the disease.
FSAF1 shares sentences with these, for which no sentence is quoted: cancer (2 papers); Alzheimer disease (1); bladder urothelial carcinoma (1); lung adenocarcinoma (1); lung carcinoma (1); Parkinson disease (1); pheochromocytoma (1); schizophrenia (1); thyroid carcinoma (1); tumour (1).